IFNG (interferon gamma)
Diseases named in the same sentence as IFNG in open-access papers (continued):
Sharing a sentence is not in itself a finding about the gene and the disease.
tumor (continued). "Moreover, the Th1 profile of the response favored the migration of IFNγ-producing CD4+ and CD8+ T cells at the tumor site, eventually contributing to the overall protective activity of vaccination." (PMID 29164053, 2017). "Interestingly, IFNγ was produced by both PD-1+ and PD-1− CD8+T cells in surrounding and tumour tissues." (PMID 28128200, 2017). "In particular, the initial expression of IFNγ by NK cells may induce expression of CXCR3 ligands and, in turn, contribute to further accumulation of NK cells and tumor rejection." (PMID 28348567, 2017). "This notion is supported by pre-clinical findings that BRAF inhibitor therapy can enhance IFNγ production, T cell proliferation and MHC expression by melanoma cells, and by clinical evidence of increased tumor-infiltrating lymphocyte populations during BRAF inhibitor therapy." (PMID 29100459, 2017). "Using TIL and tumour only specimens as controls, N=7 cases met the criteria for tumour reactivity (fivefold increase in IFNγ release) whereas the other N=3 did not." (PMID 28146145, 2017). "It is thus possible that IFNγ in the tumor microenvironment and the expression of IFN target genes in TAMs are indicators of the presence of activated, IFNγ secreting T and/or NK cells mediating anti-tumor immune responses." (PMID 28327095, 2017). "However, the predicted activation of STAT3 rather than STAT1 in the upstream analysis using Ingenuity Pathway Analysis (IPA), suggests a possible negative regulation of IFNG/STAT1 signaling, counter-balancing the inflammatory anti-tumor response." (PMID 29100312, 2017). "Taken together, we for the first time provided the rationale for the non-canonical role of IFNγ in IDC cells evading from tumour dormancy, other than immunomodulation." (PMID 29156701, 2017). "Given the importance of multifunctional effector CD8+ T cell immunity in anti-tumor immunity, we measured the Ag-specific CD8+ T cell population and its expression of IFNγ and TNFα, in response to ex vivo OVA257-264 SIINFEKL peptide stimulation, 15 days after tumor implantation." (PMID 28388572, 2017). "Tumour onset of two independent MT/ShcA+/+, MT/Shc2F/2F and MT/Shc313F/313F cell lines was unaffected in CD8+/+ versus CD8−/− or IFNγ+/+ versus IFNγ−/− animals." (PMID 28276425, 2017). "Since IL-1β is critical for priming IFNγ-producing, tumor–antigen-specific CD8+ T cells, NDK from P. gingivalis could promote the immune evasion of tumor cells." (PMID 26788120, 2016). "Compared with the control group, TNFα or IFNγ slightly but not significantly suppressed tumor growth, while TCP-1/TNFα or TCP-1/IFNγ significantly decreased tumor size compared with their unconjugated counterparts." (PMID 27342639, 2016). "As expected, multi-administration of OGNVs-miR-18a did not lead to inhibition of tumor metastasis in the NOG mice although F4/80+IFNγ+, F4/80+IL-12+ and F4/80+MHCII+ cells were still induced." (PMID 27028860, 2016). "PD-L1 can be upregulated by tumor cell oncogenes or by other mediators highly expressed within the tumor microenvironment (TME) such as tumor hypoxia, TLR-mediated signaling pathways, and IFNγ." (PMID 28031817, 2016). "In addition, downregulation of SK1 in B16 led to an increased expression of Th1 cytokines (IL-12, TNFa, IFNg) and chemokines (CCL5, CXCL9, CXCL10) into the tumor." (PMID 27708249, 2016). "A marked increase in tumor cell apoptosis in mice administered with Ad.EPCR probably stems from the combined effect of EPCR-induced specific changes in the genome of MPM cells and increased levels of IFNγ and TNFα in the pleural space." (PMID 27833109, 2016). "Additionally, we found that, compared to the tumor specific E6/E7 peptide vaccine, total tumor lysate induced higher expression of CD80 and CD40 on DCs that induced increased levels of IFNγ production upon interaction with host lymphocytes." (PMID 27223090, 2016).
tumor (continued). "To directly test whether TCP-1 peptide could deliver IFNγ to tumor vasculature, we injected 50 nmol IFNγ or TCP-1/IFNγ into mice bearing orthotopic CRC through tail veins." (PMID 27342639, 2016). "In addition to inducing tumor apoptosis, TCP-1/TNFα or TCP-1/IFNγ also increased the infiltration of CD8+ and CD4+ T cell in the tumor leading to enhanced antitumor immunity." (PMID 27342639, 2016). "Targeted delivery of TNFα or IFNγ by TCP-1 peptide exhibited better antitumor activity than unconjugated format by inducing more tumor apoptosis and also enhancing antitumor immunity shown by increased infiltration of T lymphocytes inside the tumor." (PMID 27342639, 2016). "Instead, every tested MUC1 preparation, even non-glycosylated synthetic 9mer peptides, induced interferon gamma-producing CD4+ and CD8+ T-cells that recognized glycosylated variants including tumor-associated MUC1." (PMID 26788922, 2016). "Based on the results from the LPS+IFNγ studies, we hypothesized that ADAM17 regulates Cox-2 expression in macrophages in response to tumor cell-derived factors as well." (PMID 27738494, 2016). "Blockage of PD-L1 expression on tumor cells might activate tumor-specific T cell to kill tumor cells by mediating tumor necrosis factor alpha (TNF-α) and interferon gamma (IFN-γ)." (PMID 26771840, 2016). "The generation of a tumor-specific immune response in animals undergoing complete tumor regression was assessed by secondary tumor cell challenge and splenocyte-produced IFNγ in the presence or absence of irradiated tumor cells." (PMID 27169467, 2016). "Because epitope spreading reflects an endogenous immunologic response closely related to the broader spectrum of tumor-specific preexisting immunity, we also analyzed our vaccinated patients for preexisting immunity to the vaccine by AE36-specific IFNγ-based ELISPOT assay and by LR1." (PMID 27891225, 2016). "The results demonstrated that CY+TLRa-mediated tumor rejection was strongly impaired in the absence of IFNγ-producing-T-cells." (PMID 27341020, 2016). "The joint action of interferon-gamma and TNF-α may lead to cell cycle arrest in most cancers, however, this phenomenon requires the tumor to express sTNFR1." (PMID 26928194, 2016). "Analysis of intra-tumor cytokine transcription levels suggests that AAT administration promotes a pro-cytotoxic inflammatory profile inside the tumor, including elevated transcription levels of IL-12p40, CD14, and IFNγ, and reduced transcription of IL-1Ra, VEGF, and α-SMA." (PMID 28003813, 2016). "CD19-ENG T cells secreted IFNγ after coculture with CD19-positive tumor cells (BV173, Daudi, Raji) while EphA2-ENG T cells did not (p < 0.001)." (PMID 27255991, 2016). "While increased IFNγ production by iNKT cells likely contributes to enhanced tumor control, iNKT cells do not need to generate IFNγ to mediate antitumor responses." (PMID 27471636, 2016). "Also in human cells, NK cell-secreted IFNγ and TNF induce cross-presentation of tumor cell-derived antigens by monocyte-derived DCs, promoting the induction of a tumor-specific CD8 T cell response." (PMID 27446081, 2016). "In absence of IFNγ, tumors were characterized by an important production of IL-17 and IL-6 by tumor infiltrating cells and tumor cells." (PMID 27589729, 2016). "Despite a high expression of the transcription factor T-bet, CD8+ T cells from the tumor site failed to produce IFNγ after CD3/CD28 in vitro restimulation and displayed a reduced ability to degranulate in response to T cell stimuli." (PMID 27809856, 2016). "We here chose 1 μg/mouse for TNFα which could partly inhibit tumor growth and avoid masking the action of combined treatment of TCP-1/TNFα and TCP-1/IFNγ." (PMID 27342639, 2016). "In addition, it has been shown that IFNγ+-secreting IL-17+ CD4+ T cells are increased in inflamed tissues and, importantly, have been reported to mediate tumor regression in a mouse model via an IFNγ- dependent mechanism." (PMID 26176858, 2015).
tumor (continued). "Moreover, the significant fraction of CpG-siA20 tumor lymphocytes was positive for both Trp-1-specific TCR and activation marker intracellular IFNγ." (PMID 26327508, 2015). "Hyperreactive preimmune repertoire was further supported by our observation of increased secretion of IFNγ by freshly isolated and antigen-restimulated cells – shown for Mart1, hTERT and CMV peptides in tumor-free, CMV-seronegative cHCV donors (2-way Anova p=0.0002)." (PMID 26568315, 2015). "In 52/58 cases tumor sections could be stained for the presence of CD45+ cells, the presence of Tbet+ cells, as a measure for IFNγ-producing cells, and the presence of Foxp3+ cells for regulatory T cells." (PMID 26357849, 2015). "Unlike IFNγ which acts directly on tumor cells, IFNα/β exerts its anti-tumor activity mainly through acting on immune populations, such as CD11c+ APCs, CD8+ T cells, etc." (PMID 25796556, 2015). "However, the activation of CD8+ T cells, monitored by increased expression of IFNγ after restimulation with OVA peptide, was only observed after treatment of the tumor with RT, DTIC and HT in the presence of zVAD-fmk." (PMID 25973681, 2015). "We observed an increase in IFNγ and FasL expression, compared with splenocytes obtained from tumor-bearing hamsters that received no treatment (control) or healthy (naïve) hamsters." (PMID 26671477, 2015). "In addition, tumor-infiltrating cytotoxic T cells and NK cells are major sources of IFNγ in the tumor microenvironment thus increasing IDO levels and IFNγ-mediated increase in IDO-induced resistance to FK866." (PMID 26579709, 2015). "Since NK cell recruitment may also result in release of local interferon-gamma, this might also help improve CD8+ T cell function by up-regulating tumor antigens, MHC Class I and enhanced cytotoxic activity." (PMID 25992289, 2015). "While IL-15 KO/MT tumor CD8 T cells had high levels of exhaustion markers (PD-1) and lacked IFNγ production, IL-15 TG/MT CD8 T cells had very low levels of PD-1 and produced large amounts of IFNγ." (PMID 25879689, 2015). "In non-IBC, PDL1 mRNA expression is induced in the tumor microenvironment by activated TILs through the release of IFNγ." (PMID 25940795, 2015). "However, only T cells of mice whose tumor was treated with RT, DTIC and HT in combination with zVAD-fmk expressed significant higher amounts of IFNγ after re-stimulation." (PMID 25973681, 2015). "IL-12 further induces proliferation and cytotoxic activity of natural killer (NK) cells and generates anti-tumor activity through effector cell production of cytokines, including interferon-gamma (INF-γ), which in turn up-regulates Fas (CD95) and FasL on tumor cells." (PMID 25890361, 2015). "IFNγ production by ROR1RCD137+ T cells slightly increased only in response to Kasumi-2 cells, demonstrating that there were differences in the effector cytokine production of the two CAR populations to certain tumor cells." (PMID 26030772, 2015). "Moreover, tumor-specific CTL produce a large amount of IFNγ, which increases expression of MHC class I molecules and Fas on cancer cells, thus leading to enhanced granule- and death ligand-mediated tumor cytotoxicity." (PMID 25760243, 2015). "Furthermore, an increase in potentially anti-tumorigenic IFNγ producing CD4+ and CD8+ T cells also indicate improved anti-tumor immunity." (PMID 26061815, 2015). "Although IFNγ was not predicted to be activated or inhibited with upstream regulator analysis for old non-tumor bearing mice, we observed that the overall influence of the key genes involved for this condition down-regulated IFNγ." (PMID 26497558, 2015). "HPV-positive tumor tissue-derived cell cultures produced markedly higher levels of chemokines, namely CXCL9, CXCL10, CXCL12, CCL17 and CCL21, and slightly higher levels of the cytokines IL-2, IL-17, IL-23 and IFNγ." (PMID 25949860, 2015).
tumor (continued). "Our data demonstrate that IFNγ-mediated activation of the APM genes and MHC class I expression in two tumour cell lines with reversible MHC class I expression defects was strongly associated with DNA demethylation of multiple APM genes located in the MHC locus." (PMID 25071011, 2014). "To determine if blockade of CD1d resulted in improved priming of anti-tumor CD8+ T cells in dLN of WT mice treated with local radiotherapy and anti-CTLA-4 mAb, we measured tumor antigen-specific production of IFNγ by dLN cells stimulated with a CD8 T cell epitope derived from the tumor antigen gp70." (PMID 25349699, 2014). "MHC class I expression on tumour cells after IFNγ treatment was upregulated as compared to the tumour cells without treatment." (PMID 25071011, 2014). "In short, the physiological importance of immune surveillance was well revealed by the pathological consequences of its failure: the neutralization of IFNγ with antibodies and later the use of mice lacking IFNγ responsiveness was shown to enhance tumor growth." (PMID 25101088, 2014). "Presumably, in mice treated with 1D11+CY, the 4T1 tumor-specific immune responses were mediated by IFNγ-producing T cells, and non-specific anti-cancer immune responses were mediated by inflammatory myeloid cells." (PMID 24416401, 2014). "Serum lactoferrin (LF), serum glutathione-s-transferase enzyme (GST), interferon gamma (INF-γ), tumor marker carcinoembryonic antigen (CEA), renal function tests, hepatic function tests, and complete blood count were measured for both groups before and at the end of the trial." (PMID 27350986, 2014). "Among tumor-derived factors that activate fibroblasts are TGFβ, PGE, TNF, IFNγ, and IL6." (PMID 24818101, 2014). "For the first time, we present evidence that WT mice have reduced numbers of DCs in tumor and dLN compared to iNKT−/− mice, and reduced priming of tumor-specific CD8+ T cells, as measured by gamma interferon (IFNγ) production in response to a H2-Ld-restricted peptide derived from a tumor antigen." (PMID 25349699, 2014). "By suppressing interferon-gamma expression and release from antigen-specific T cells, and locally enhanced IL-4 and IDO levels COX-2 may contribute to a tumor-permissive milieu." (PMID 25501829, 2014). "We found that the number of macrophages and levels of IFNγ and CCL4 mRNA were markedly reduced in tumors from CHOP KO relative to wt mice, suggesting a role for CHOP in modulating tumor microenvironment and macrophage recruitment to the tumor." (PMID 24339898, 2013). "Co-culture of anti-KIT dTc with KIT- control tumor cells did not result in significant IFNγ production (data not shown)." (PMID 23433424, 2013). "Analyses of purified tumor-infiltrating CD45+ cells indicated that Lov treatment increased mRNA levels for M1 markers, which was statistically significant for IFNγ and IL-1β, whereas it downregulated M2-like markers (with significant differences for IL-10, CD206 and CCL22)." (PMID 24317954, 2013). "In mice challenged with MB49, which expresses the HY antigen complex, T cell responses primed by the tumor with and without Val-boroPro were measured using interferon gamma ELISPOT." (PMID 23554941, 2013). "Moreover, this tumor recognition was TCR dependent, as the IFNγ secretion was reduced to background levels in the presence of an MHC class I blocking antibody." (PMID 23402380, 2013). "This potential probiotic mechanism was further proven by studies finding Lactobacillus strains induced APC production of IL-12, leading to NK activation and NK-derived IFNγ secretion, which not only has implications to innate responses but also CMI-mediated anti-tumour responses." (PMID 23760057, 2013). "Although IL-4, IFNγ, and several other tumor-derived cytokines and growth factors modulate macrophage phenotypes in vitro and in vivo, the molecular mechanisms that promote M1 or M2 TAM subsets within the tumor microenvironment are incompletely understood." (PMID 22938502, 2012).
tumor (continued). "Flow cytometric evaluation of spleens of mice that had rejected a secondary tumor rechallenge showed an enhancement in the CD4+CD44+ and CD8+CD44+ T cell memory markers as well as an enhanced secretion of IFNγ by memory T cells in response to OVA stimulation in vitro." (PMID 22815789, 2012). "In contrast, these same high avidity T cells produce multiple cytokines (IFNγ, IL-2, and TNFα) when transferred into tumor-bearing non-tolerant FVB/N mice." (PMID 22359647, 2012). "Apart from the direct cytotoxic activity of TNF and IFNγ against MC38CEA cells, the cytokines may influence in vivo tumor growth also through modulating immune response." (PMID 23251384, 2012). "To evaluate this hypothesis we have measured the concentration of selected cytokines: TNF, IFNγ, IL-12 (p70), MCP-1, IL-6, and IL-10 in the tumor lysates and in the sera taken from mice at the time of their sacrifice." (PMID 23251384, 2012). "At the same time, serum levels of TNF, IFNγ, and MCP-1 were lower in mice bearing ADAM17-silenced tumors than mock-transfected ones, which is not surprising as serum levels of the cytokines usually correlate with the tumor size." (PMID 23251384, 2012). "M1 cells, when stimulated by LPS or IFNγ/TNF induce production of IL-1, TNF, IL-6, IL-23, IL-12, and IL-10, which can be involved in a DTH response, type 1 inflammation, Th1 responses, promoting anti-tumor activity." (PMID 21281484, 2011). "A high proportion of the tumor-infiltrating CD4+ T cells from this model produce IL-13 and IFNγ." (PMID 21281484, 2011). "The antiproliferative effect of IFNγ on both types of cells, however, remained significant, suggesting that its efficiency was not affected by the paracrine interactions between tumor and stellate cells." (PMID 21310022, 2011). "Using a mouse model of heterotopic PC, we initially studied how IFNγ affects the growth of tumor cells in the presence and absence of co-injected PSC." (PMID 21310022, 2011). "IL10 and IFNγ were chosen as these are not produced by the tumor cell line and their presence denotes expression by immune or other urothelial cells." (PMID 22013484, 2011). "Direct co-incubation of WSX1-positive tumor cells and purified CD3+ T or NK cells inhibits T cell numbers or NK cell's ability to produce IFNγ whereas neither T, neither NK, nor tumor cells express IL27." (PMID 21559505, 2011). "We hypothesise that the enhanced tumour cell proliferation is accompanied by inhibition of the TGF-β signalling pathway in the (human) tumour cells via various stromal-derived mouse cytokines such as IL7 and IFNG." (PMID 22045186, 2011). "However, STAT1 is the major effector of IFNγ, which is antiproliferative or tumoricidal in several cancer cell types; although STAT3-decoy ODN has been found to induce tumor cell death in several different cell systems, it can also inhibit STAT1." (PMID 21486470, 2011). "Spleen cells analyzed by ELISPOT for IFNγ secretion, using immunodominant MAA peptides of tyrosinase and gp100, were found to include a much higher proportion of tumor specific T cells in tumor bearing mice treated with α-gal glycolipids than in mice with tumors injected with PBS." (PMID 23087817, 2010). "Given that upregulation of IgG in tumor areas correlates with ICI immune-therapy 29, and that our study indicated that GIC-A tumors presented significantly lower TIDE scores and exclusion scores, but significantly higher IFNG expression, and dysfunction scores." (PMID 41510151, 2026). "With single-cell RNA analysis on 13 paired tumor samples from 6 CD30+ MF patients, we revealed that BV-induced immunogenic cell death (ICD) in both CD30+ and CD30- malignant T cells while specifically enhanced interferon-α (IFNα) and IFNγ responses in CD30- subsets." (PMID 41762706, 2026).